SERPINB10 (serpin family B member 10)
Description:
Protease inhibitor that may play a role in the regulation of protease activities during hematopoiesis and apoptosis induced by TNF. May regulate protease activities in the cytoplasm and in the nucleus.
Synonyms: PI-10; PI10
Tractability: Antibody: its Gene Ontology location is reachable by antibodies, with high confidence.
Gene: Protein-coding gene on chromosome 18 (63,907,958 to 63,936,111, forward strand). Ensembl gene ENSG00000242550.
Subcellular location: Nucleus; Cytoplasm
Subcellular location (Human Protein Atlas): Nucleoplasm; Cytosol
Pathways (Reactome):
Immune System: Neutrophil degranulation
Gene Ontology:
Molecular function: serine-type endopeptidase inhibitor activity
Cellular component: cytosol; nucleoplasm; ficolin-1-rich granule membrane; plasma membrane; secretory granule membrane; cytoplasm; nucleus
Genetic constraint (gnomAD): Loss-of-function variants: 23 observed, 31.18 expected, observed/expected ratio (o/e) 0.74, 90% interval 0.53 to 1.04. The upper end of that interval is the gene's LOEUF score, 1.04, which puts it in group 4 of 6, group 1 being the genes least tolerant of losing a copy. Missense variants: 471 observed, 426.52 expected, observed/expected ratio (o/e) 1.1, 90% interval 1.02 to 1.19. Synonymous variants: 164 observed, 150.39 expected, observed/expected ratio (o/e) 1.09, 90% interval 0.96 to 1.24.
Homologues: Orthologues: chimpanzee SERPINB10 (98% identical), macaque SERPINB10 (95% identical), pig SERPINB10 (81% identical), rabbit SERPINB10 (80% identical), dog SERPINB10 (79% identical), mouse Serpinb10 (75% identical), rat Serpinb10 (72% identical). Paralogues in human: SERPINB2 (48% identical), SERPINB1 (46% identical), SERPINB3 (45% identical), SERPINB6 (45% identical), SERPINB4 (45% identical), SERPINB9 (44% identical), SERPINB13 (44% identical), SERPINB8 (44% identical), SERPINB12 (42% identical), SERPINB11 (42% identical), SERPINB5 (36% identical), SERPINB7 (33% identical), and 24 more.
Diseases named in the same sentence as SERPINB10 in open-access papers:
SERPINB10 is named in the same sentence as 22 diseases in open-access papers, as found by Europe PMC text mining. Sharing a sentence is not in itself a finding about the gene and the disease. The quoted sentences say what the papers report.
asthma (8 papers, 2020 to 2024). "A variety of immune cells associated with SERPINB10, such as neutrophils and dendritic cells, have also been shown to play an important role in asthma through autophagy." (PMID 35619697, 2022). "SERPINB10 is another member of clade B. Previously, we reported that SERPINB10 expression was increased in the bronchial epithelial cells of patients with asthma and was associated with airway eosinophilic inflammation." (PMID 34126986, 2021). "A study on ERPINB10-knockdown mice found that these groups of mice had diminished numbers of Th2 cells and were more susceptible to apoptosis, indicating that SERPINB10 may contribute to allergic inflammation and the Th2 response of asthma by inhibiting the apoptosis of Th2 cells." (PMID 35550122, 2022). "Studies showed that increased levels of SERPINB10 mRNA in epithelial cells of patients with asthma can lead to allergic airway inflammation, which is positively correlated with AHR, sputum eosinophil percentage, and exhaled nitric oxide content." (PMID 35619697, 2022). "Serine peptidase inhibitor, clade B, member 10 (SERPINB10) contributes to allergic inflammation in asthma." (PMID 34126986, 2021). "Knockdown of SERPINB10 expression can reduce airway hyperresponsiveness and airway eosinophilic inflammation in a murine model of asthma." (PMID 34126986, 2021). "Here we showed, for the first time, that SERPINB10 has a protective effect upon Th2 cells in people with asthma and in mice challenged by HDM." (PMID 34126986, 2021). "We measured expression of SERPINB10 in polarized Th1 and Th2 cells derived from patients with asthma." (PMID 34126986, 2021). "Second, we sorted naïve CD4 T cells from the peripheral blood of asthma patients and explore the expression and the role of SERPINB10 in Th1 and Th2 cells." (PMID 34126986, 2021). "SERPINB10, a proinflammatory cytokine, was demonstrated to be upregulated in bronchial epithelial cells and could promote the Th2 inflammatory response in asthma patients and murine models." (PMID 36398030, 2022). "The ERPINB10 gene is regulated by miR-876-5p and miR-2681-3p, and the downregulation of miR-876-5p and miR-2681-3p may lead to the upregulation of SERPINB10 gene in asthma." (PMID 35619697, 2022). "Our data suggested that SERPINB10 may contribute to airway inflammation and the Th2 response of asthma by regulating apoptosis of Th2 cells." (PMID 34126986, 2021). "We showed that targeting of SERPINB10 expression by shRNA significantly decreased the number of Th2 cells in mouse lungs, and promoted the apoptosis of Th2 cells in patients suffering from asthma." (PMID 34126986, 2021). "SERPINB10 was expressed in polarized Th2 cells from patients with asthma." (PMID 34126986, 2021). "Our results suggest that SERPINB10 may contribute to allergic inflammation and the Th2 response of asthma by inhibiting the apoptosis of Th2 cells." (PMID 34126986, 2021). "To clarify further the functional importance of upregulation of SERPINB10 expression in Th2 cells, we sorted naïve CD4 T cells from the peripheral blood of asthma patients and transduced them with lentivirus encoding control shRNA or shRNA specific for SERPINB10." (PMID 34126986, 2021). "SERPINB10 may represent a therapeutic target for alleviation of the Th2 response in asthma." (PMID 34126986, 2021). "We demonstrated that knockdown of SERPINB10 expression alleviated allergic inflammation and Th2 responses in an HDM model of asthma." (PMID 34126986, 2021). "We used an HDM-induced asthma model and knocked down SERPINB10 expression by transfection with AAV against SERPINB10." (PMID 34126986, 2021). "We investigated the effect of knockdown of SERPINB10 expression on the Th2 response and apoptosis of Th cells in a house dust mite (HDM)-induced model of asthma." (PMID 34126986, 2021). "The type 2 status of asthma was defined by the expression of the type 2 signature genes (CLCA1, POSTN, and SERPINB10) in the epithelial brushings as previously reported." (PMID 33945508, 2021).
COVID-19 (3 papers, 2023 to 2025). A disease caused by infection with severe acute respiratory syndrome coronavirus 2. "In terms of relevance to COVID-19 vulnerability, SERPINB10, SERPINE1, and SERPINA3 paint very different pictures." (PMID 37987478, 2023). "There is minimal evidence that SERPINB10 plays any differential role, whether exacerbatory or mitigative, in determining COVID-19 outcomes." (PMID 37987478, 2023).
food allergy (2 papers, 2019 to 2020). Gastrointestinal disturbances, skin eruptions, or shock due to allergic reactions to allergens in food. "In terms of genetic susceptibility in epithelial genes a recent GWAS demonstrated a strong association between the SERPINB10 gene and susceptibility to multiple food allergies." (PMID 33365031, 2020). "This gene is known to be expressed by epithelial cells and involved in IL-13-induced transcriptional changes in bronchial epithelial cells, suggesting a possible role for epithelial SERPINB10 in mediating susceptibility to food allergy." (PMID 33365031, 2020).
myeloid leukaemia (2 papers, 2010 to 2021). "SerpinB10 (SPB10), also known as Bomapin, is a redox-sensitive nucleocytoplasmic protein that promotes proliferation of hematopoietic and myeloid leukemia cells under basal conditions, although it also enhances apoptosis following withdrawal of growth factors." (PMID 34445206, 2021).
allergic asthma (1 paper, 2021). A asthma with a basis in a pathological type I hypersensitivity reaction. "The goal of this study was to unveil the function of SERPINB10 in the Th2 response of allergic asthma and the mechanism by which SERPINB10 affects the viability of Th2 cells." (PMID 34126986, 2021). "We wished to investigate the role of SERPINB10 in the Th2 response of allergic asthma." (PMID 34126986, 2021). "Further studies will clarify if SERPINB10 protects ILC2 cells from apoptosis in allergic asthma." (PMID 34126986, 2021). "Our findings suggest that SERPINB10 may promote allergic asthma by inhibiting the apoptosis of Th2 cells." (PMID 34126986, 2021). "Therefore, we hypothesized that SERPINB10 may participate in the Th2 response of allergic asthma by affecting the apoptosis of Th2 cells." (PMID 34126986, 2021). "The role of SERPINB10 in the Th2 response of allergic asthma is not known." (PMID 34126986, 2021).
polyp (1 paper, 2022). A usually exophytic mass attached to the underlying tissue by a broad base or a thin stalk. "Therefore, we speculated that tissue with higher levels of SERPINB10 could augment Th2 inflammatory response and promote eosinophil recruitment in polyp tissue, which leads to a worse prognosis and a higher risk of recurrence in CRSwNP." (PMID 36398030, 2022).
Sepsis (1 paper, 2025). Sepsis is defined as life-threatening organ dysfunction caused by a dysregulated host response to infection. "Only a small number of host genes were differentially expressed between the Gram-positive (HLA-B, SERPINB10, LOC105377885, CEACAM6, NIPA2) and Gram-negative (CBFA2T3, LOC107987303, MARCO) sepsis samples in our cohort." (PMID 40965975, 2025).
infection (3 papers, 2017 to 2024). The state of being infected such as from the introduction of a foreign agent such as serum, vaccine, antigenic substance or organism. "Anti-apoptotic factors including serine protease inhibitors (SERPINB10, SERPINA3–8 (Serpin domain-containing protein, LOC106504547), and SERPIN11A) and heat shock proteins (HSP70.2 and HSPA6), were only found after infection with swH1N1 compared to control." (PMID 39247193, 2024). "In particular, some genes involved in immune/inflammatory responses and infection (e.g., IL19, MAPK15, and SERPINB10) and components of a complement system (e.g., C4B, VTN, BDKRB1, and C4BPA) have not been previously reported regarding their expression and functions in human omental adipose tissue." (PMID 30816281, 2019).
inflammation (2 papers, 2021 to 2022). Aberrant reaction of the microcirculation characterized by movement of fluid and leukocytes from the blood into extravascular tissues. "Epithelial SERPINB10 contributes to allergic eosinophilic inflammation." (PMID 32830257, 2021).
tumor (1 paper, 2013). "Moreover, the mutations ALPK2.R136S, CHST9.S122N, FAM38B.V2463, LAMA1.S1577A, LAMA1.K2002E, MYOM1.T215M, SERPINB10.R246C and SLC14A2.A880T were found in all three tumor samples and shared a similar frequency profile." (PMID 23892400, 2013).
SERPINB10 also shares sentences with these, for which no sentence is quoted: emphysema (10 papers); chronic bronchitis (2); pneumonia (2); bronchiectasis (1); chronic lower respiratory disease (1); chronic obstructive pulmonary disease (1); chronic rhinosinusitis (1); cutaneous leishmaniasis (1); leishmaniasis (1); lung disease (1); Neonatal sepsis (1); peanut allergy (1).